GLP1R (glucagon like peptide 1 receptor)
Diseases named in the same sentence as GLP1R in open-access papers (continued):
Sharing a sentence is not in itself a finding about the gene and the disease.
asthma (24 papers, 2017 to 2026). "Based on this, glycation modulation by GLP-1R agonists and decrease in oxidative stress by metformin, may explain their association with improved asthma control in individuals with obesity and asthma." (PMID 36837831, 2023). "Furthermore, GLP-1R activation is associated with the modulation of inflammation and immune responses, processes that are also regulated by muscarinic receptor activity in inflammatory conditions, such as asthma." (PMID 40474934, 2024). "In keeping with these effects of insulin on ASM, treatment with anti-diabetic medications, including metformin, a biguanide, and albiglutide, a glucagon-like peptide-1 receptor (GLP-1R) agonist, have been associated with decreased asthma disease burden." (PMID 36837831, 2023). "Similar to metformin, GLP-1 receptor (GLP-1R) agonists have also been shown to have beneficial effects on asthma." (PMID 37893170, 2023). "The GATA-3 study design serves as an example of the first placebo-controlled trial to evaluate the glucagon-like peptide 1 receptor pathway’s role in asthma management independent of weight loss." (PMID 41567689, 2026). "Interestingly, emerging therapeutic investigations have demonstrated the potential benefits of employing glucagon-like peptide-1 receptor agonists and metformin to reduce asthma exacerbations in individuals who have both type 2 DM and asthma." (PMID 38343638, 2024). "Recent data illustrate the potential for GLP-1R agonists to treat obese asthma." (PMID 38878250, 2024). "GLP-1RAs may also be a therapeutic target for asthma as animal models show that these drugs reduce allergen-induced airway inflammation, as the GLP-1R is expressed on lung epithelial and endothelial cells." (PMID 40474934, 2024). "GLP-1R agonist treatment has also shown a beneficial role in treating asthma in obese mice." (PMID 37893170, 2023). "In addition to modulating ASM tone, GLP-1R activation may also reduce pro-inflammatory cytokine release, contributing to an anti-inflammatory effect that could be beneficial for asthma management." (PMID 40474934, 2024). "However, a recent network meta-analysis found that GLP-1R agonists did not significantly affect the risk of asthma incidents." (PMID 38542187, 2024). "Using the GLP-1R Agonists in the Treatment of Adult, Symptomatic, Obese Asthma (GATA-3) trial (ClinicalTrials.gov NCT05254314) as a conceptual framework, we propose an evolved model for future asthma research." (PMID 41567689, 2026). "Although metformin is a standard therapy for prediabetes and GLP-1R agonist use is increasing in children, their effectiveness in childhood obesity-related asthma is not known." (PMID 36837831, 2023). "Furthermore, clinical trials are ongoing to assess the efficacy of non-biologics in the treatment of obese asthma, including a glucagon-like peptide-1 receptor agonist, a Janus kinase inhibitor, and probiotics." (PMID 38878250, 2024). "The lower level of GLP-1R in asthma than in healthy subjects indicates that the eosinophil response to activating stimuli may be more regulated by GLP-1 in healthy persons and that eosinophil activation may be more easily achieved in asthma than in health." (PMID 28660189, 2017).
breast carcinoma (24 papers, 2018 to 2026). "Data presented at the American Society of Clinical Oncology annual meeting indicate that patients who take GLP-1R therapies during breast cancer treatment can achieve clinically meaningful weight loss, which may improve their prognosis." (PMID 41178720, 2025). "To better understand the heterogeneity of GLP-1R within a specific tumor histology, we more carefully examined the breast cancer subtypes." (PMID 41542041, 2026). "To more carefully define robust GLP-1R expression in breast cancer cells we focused on cell lines with log (TPM+1) > 0.2." (PMID 41542041, 2026). "In that study, referrals for diagnostic breast imaging and mammography screening also increased with increasing weight loss category, again suggesting a better ability to diagnose breast cancer in women taking GLP-1R agonists." (PMID 41178720, 2025). "cAMP-response element binding protein (CREB), a crucial downstream target of PKA, effectively suppresses breast cancer cell proliferation following GLP-1R activation." (PMID 40140925, 2025). "Studies have demonstrated that GLP-1R is expressed on human breast cancer cell lines as well as primary breast cancer tissue." (PMID 41157306, 2025). "Another study showed that GLP-1R was widely expressed in many human breast cancer cell lines, including MCF-7, MDA-MB-231, BT483, MDA-MB-468, and ZR751, via RT-PCR and Western blot analyses." (PMID 41157306, 2025). "Application of α-conotoxins have also extended towards the development of stable peptidomimetics for other receptor types, such as the glucagon-like peptide-1 receptor as well as a medium of targeted drug delivery in breast cancer." (PMID 29899286, 2018). "The use of glucagon-like peptide-1 receptor agonists (GLP1-RA) for weight loss is increasing; implications in breast cancer survivors remain unclear." (PMID 41677473, 2026). "They discovered that the GLP‐1R antagonist exendin completely reversed the antiproliferative effect of exendin‐4 and that GLP‐1R knockdown eliminated the reduction in MCF‐7 cell numbers by exendin‐4, suggesting that exendin‐4 reduces breast cancer cell numbers through GLP‐1R activation." (PMID 40552446, 2025). "Large retrospective studies demonstrate that the risk for breast cancer is not elevated in people using GLP-1R agonists, particularly with follow-up of more than 2 years, nor is there excess risk for benign or premalignant breast neoplasms." (PMID 41178720, 2025). "In the clinical setting, once a patient is diagnosed and cancer treatment begins, physicians might choose to stop GLP-1R therapy, which could indirectly promote breast cancer progression through weight regain." (PMID 41178720, 2025). "One study found a greater risk of breast cancer diagnosis in patients using GLP-1R therapies who had no prior history of mammography screening, but not in those who had a history of regular mammograms." (PMID 41178720, 2025). "Although GLP-1R’s role is not fully understood or investigated in breast tissue when activated by different agonists, it may increase or decrease the progression of breast cancer." (PMID 38801466, 2024). "Evaluation of the role of genetically proxied GLP1R signaling, alone and in combination with genetically proxied GIPR signaling, could provide additional insight into the viability of dual pharmacological GLP1R/GIPR agonism for breast cancer prevention." (PMID 37250804, 2023). "However, another recent study showed that the immunoreactivity of GLP-1R was significantly higher in breast cancer tissues of diabetic patients." (PMID 36386208, 2022). "Furthermore, as we detect GLP-1R expression in a variety of solid and liquid malignancies these results may extend beyond the breast cancers examined here." (PMID 41542041, 2026).
breast carcinoma (continued). "Considering the significantly elevated expression levels of GLP-1R in diabetic patients, it is hypothesized that administration of GLP-1R agonists may elevate the risk of breast cancer progression in these patients, thus necessitating particular caution in clinical management." (PMID 40140925, 2025). "To determine if GLP-1R expression is sufficient to confer sensitivity to GLP-1 agonists we obtained representative GLP-1R+ and GLP-1R- breast cancer cell lines." (PMID 41542041, 2026). "The breast cancer cell lines were stratified by the three predominant subtypes (ER+, HER2+ and TNBC) and GLP-1R transcript expression was interrogated." (PMID 41542041, 2026). "Among the breast cancer cell lines, MCF-7 cells, which display high estrogen-sensitive proliferation, had the highest GLP-1R gene expression as measured by quantitative real-time PCR (RT-PCR)." (PMID 41157306, 2025). "Moreover, GLP-1R agonists, including liraglutide, have been shown to inhibit proliferation, cell cycle progression, and/or migration in lung, pancreatic, prostate, endometrial, and murine colon cancer cells, although they were reported to promote the proliferation of breast cancer cells." (PMID 39777709, 2025). "The activation GLP-1R by GLP-1RA can restrain the activation of NF-κB, thereby facilitating the apoptosis of breast cancer cells and inhibiting their proliferation." (PMID 39371922, 2024). "Taken together, this analysis identifies robust GLP-1R expression in a subset of ER-negative, but not ER+, breast cancer cell lines." (PMID 41542041, 2026). "However, in highly invasive breast cancer cell lines MDA-MB-231 and MDA-MB-468, high concentrations (100 nM) of liraglutide promote breast cancer progression by activating GLP-1R via the NOX4/ROS/VEGF signaling pathway." (PMID 40140925, 2025). "In addition, transfection of MCF-7 cells using a GLP-1R-expressing lentiviral vector containing a Flag epitope tag showed exclusive GLP-1R expression to the breast cancer cell membrane rather than the cytosol or nucleus." (PMID 41157306, 2025). "Importantly, ER+ breast cancer cell lines were uniformly negative for GLP-1R, and immunotherapies are not currently approved for this subtype, suggesting that certain cancer subtypes could be safely treated with concurrent GLP-1RAs." (PMID 41542041, 2026).
coronary artery disease (24 papers, 2010 to 2025). "Our empirical focus is to use genetic variants in the GLP1R gene region to understand the mechanism by which GLP1R agonism affects coronary artery disease (CAD) risk." (PMID 38379245, 2024). "In addition, carriers of genotype GG at rs4714210 in GLP1R showed a decreased risk of coronary heart disease." (PMID 38131033, 2023). "Moreover, GLP1R polymorphisms are associated with lipid metabolism and the risk of coronary artery disease in T2DM patients." (PMID 38131033, 2023). "A recent study showed that the mRNA expression of GLP-1R was considerably associated with the components of the renin-angiotensin-aldosterone system (RAAS) detected in epicardial and pericardial fat in patients with severe coronary artery disease." (PMID 36865917, 2023). "In a recent clinical study, we reported that the expression of GLP-1R on macrophages, especially M2 marcrophages, was significantly reduced in patients with coronary heart disease (CHD), suggesting a potential role of macrophage-derived GLP-1R signaling in cardiovascular disease." (PMID 36569936, 2022). "Observations from preclinical studies will be compared to their clinical counterparts, while being further interrogated to define potential mechanisms that may account for SGLT2 inhibitor or GLP-1R agonist-induced cardioprotection against ischemic heart disease." (PMID 35832485, 2022). "For example, GLP-1R agonists improve outcomes in ischemic heart diseases; however, this beneficial effect does not require cardiomyocyte GLP-1R." (PMID 37754815, 2023). "Nonetheless, that does not necessarily imply that a GLP-1R agonist is the superior glucose-lowering agent versus an SGLT2 inhibitor for an individual with T2DM and coexisting ischemic heart disease." (PMID 35832485, 2022).
medullary thyroid carcinoma (23 papers, 2012 to 2025). "Animal and human observational data suggest an increased risk of medullary thyroid carcinoma after treatment with glucagon-like peptide-1 receptor agonists." (PMID 38004062, 2023). "Nonetheless, the FDA issued a warning for most GLP-1R–targeted therapies for patients with a history of medullary thyroid carcinoma or multiple endocrine neoplasia syndrome, which remains in place today." (PMID 41178720, 2025). "These drugs target GLP-1R, and their use in neuroendocrine cancer patients with medullary thyroid carcinoma (thyroid NET) or multiple endocrine neoplasia syndrome type 2 is deemed contraindicated." (PMID 41312422, 2025). "While GLP-1RAs are contraindicated for medullary thyroid carcinoma, we found 0 of 29 thyroid NETs expressed GLP-1R." (PMID 41312422, 2025). "Nevertheless, GLP-1R expression was found in thyroid glands of 20, 91, and 100% of patients with papillary carcinoma, medullary thyroid cancer (MTC), and C-Cell hyperplasia, respectively." (PMID 23641235, 2013). "These agents are contraindicated in patients with thyroid NETs (i.e., medullary thyroid carcinoma) or multiple endocrine neoplasia type 2 (MEN2) based on rodent studies suggesting that GLP-1RAs promote tumor growth via activation of GLP-1R on rodent thyroid C-cells." (PMID 41312422, 2025). "Finally, the use of injectable GLP-1R agonist or GIP/GLP-1R–based medications is contraindicated in patients with a personal or family history of medullary thyroid carcinoma or patients with type 2 multiple endocrine neoplasia syndrome." (PMID 40568728, 2025). "Other authors pointed out that the rare presence of GLP-1R-positive medullary thyroid carcinoma might be a candidate for in vivo scintigraphy and targeted radiotherapy." (PMID 39598383, 2024). "Furthermore, medullary thyroid carcinomas are noteworthy because of important species differences in their GLP-1R expression." (PMID 23230431, 2012). "In rats, virtually all medullary thyroid carcinomas expressed GLP-1Rs in high amounts, while in humans only 28% expressed GLP-1R at low density levels." (PMID 23230431, 2012). "This is in part because preclinical data show that GLP-1R agonists, including GLP-1 itself, can increase the proliferation of parafollicular C cells in the thyroid gland of rats, and in a C cell line derived from a rat medullary thyroid carcinoma." (PMID 41178720, 2025). "Glucagon-like peptide-1 receptor agonists (GLP-1 Ra) is a group of medications used to treat type 2 diabetes that has documented C-cell stimulation effect in rodents, leading to subsequent CCH and medullary thyroid carcinoma (MTC) in rats and/or mice." (PMID 36751230, 2023).
acute kidney injury (22 papers, 2013 to 2026). Sudden and sustained deterioration of the kidney function characterized by decreased glomerular filtration rate, increased serum creatinine or oliguria. "In a mouse model of acute kidney injury caused by sepsis, the expression of GLP-1R in the renal tubules increases in the early stage of sepsis, and the endogenous GLP-1 regulation reduces kidney injury." (PMID 34335269, 2021). "Similar results were reported in a meta-analysis that GLP-1R agonists reduced the incidence of renal failure in patients with T2DM." (PMID 39858999, 2024). "GLP-1R is thought to be expressed in the glomeruli and proximal tubule, with increased expression evident in an ischemic reperfusion model of acute kidney injury." (PMID 30823876, 2019). "Clinical studies after marketing have shown that the use of glucagon-like peptide-1 receptor agonist(GLP-1RA) may lead to acute kidney injury(AKI)." (PMID 36583004, 2022).
prostate carcinoma (22 papers, 2012 to 2026). A carcinoma that arises from epithelial cells of the prostate gland. "In vivo, Ex-4 has been demonstrated to inhibit prostate cancer cell growth by activating GLP-1R, reducing s-phase kinase-associated protein-2 (SKP2) gene expression, subsequently increasing p27Kip1 (p27) protein levels, and inducing tumor cell cycle arrest." (PMID 40140925, 2025). "GLP-1R agonist use consistently associates with a lower risk for prostate cancer in clinical studies." (PMID 41178720, 2025). "It is interesting that such a reduced risk of prostate cancer related to incretin-based therapies is also observed in a recent clinical trial on liraglutide, a GLP-1R agonist, showing a hazard ratio (95% confidence interval) of 0.54 (0.34-0.88)." (PMID 27661113, 2017). "In the research, they showed that the presence of GLP-1R in human prostate cancer cells was inversely associated with cancer growth and that increasing GLP-1R levels inhibited the growth of prostate cancer cells by slowing down cell division both in laboratory settings and in living organisms." (PMID 39429275, 2024). "Finally, GLP1R agonist use has been associated with a decreased risk of prostate cancer when compared with sulfonylurea use." (PMID 37171501, 2023). "Lentiviral overexpression of GLP-1R has also been demonstrated to attenuate prostate cancer cell proliferation by inhibiting cell cycle progression." (PMID 39777709, 2025). "The level of GLP-1R expression showed an inverse correlation with both the Gleason score and the growth of prostate cancer in human prostate cancer." (PMID 39429275, 2024). "Immunohistochemical analysis of human prostate cancer tissues has revealed strong expression of GLP-1R, indicating its presence in prostate cancer cells." (PMID 39465848, 2024). "In fact, GLP-1R expression has been found to be co-localized with P504S, a prostate cancer marker, in human prostatectomy specimens." (PMID 39931650, 2024). "The GLP-1R antagonist and the protein kinase A inhibitor (PKI) canceled the antiproliferative effect of Ex-4, which suggests that the Ex-4 reduces prostate cancer cell proliferation due to GLP-1R activation which results in inhibition of ERK-MAPK." (PMID 33921222, 2021). "The Japanese investigators showed that GLP-1R is expressed in human prostate cancer tissue and exendin-4 (a GLP-1R agonist) significantly decreased the proliferation of prostate cancer cells that expressed GLP-1R." (PMID 27661113, 2017). "In the present study, we demonstrated that the GLP-1R agonists, Ex–4 and metformin, significantly and additively decreased prostate cancer growth." (PMID 26439622, 2015). "Only ovarian and prostate carcinomas rarely showed GLP-1R at low levels, while breast, colorectal, gastric, pancreatic, hepatocellular, and cholangiocellular as well as lung carcinomas (non-small and small cell carcinomas) were negative for GLP-1R." (PMID 23230431, 2012). "Multiple recent meta-analyses covering studies that included a variety of controls, such as metformin, insulin, DPP4 inhibitors, SGLT2 inhibitors, sulfonylureas, and TZDs, demonstrated a reduction in prostate cancer incidence in men with T2D who took GLP-1R therapies." (PMID 41178720, 2025). "Both in vitro and in vivo experiments utilizing GLP-1R agonist exendin-4 demonstrated decreased proliferation of prostate cancer cell lines by inhibiting the extracellular signaling-regulated kinase/mitogen-activated protein kinase (ERK/MAPK) pathway, independent of the androgen receptor axis." (PMID 39931650, 2024). "This suggests that GLP-1R expression in prostate cancer may be negatively correlated with cancer progression." (PMID 39465848, 2024). "Up-regulation of GLP-1R induced by the combined treatment with Ex–4 and metformin may be one of the mechanisms by which Ex–4 and metformin additively attenuate prostate cancer growth." (PMID 26439622, 2015).